TREM2 (triggering receptor expressed on myeloid cells 2)
Diseases named in the same sentence as TREM2 in open-access papers (continued):
Sharing a sentence is not in itself a finding about the gene and the disease.
mycobacterial infection (1 paper, 2021). "Since our data suggested a suppressive role for TREM2 in the microbicidal innate immune response via Mincle, we investigated the impact of TREM2 deficiency on the clearance of mycobacterial infection." (PMID 33863908, 2021). "Moreover, loss of TREM2 markedly enhances Mincle-induced macrophage activation in vitro and inflammation in vivo, and accelerated the elimination of mycobacterial infection in mice." (PMID 33863908, 2021). "Collectively, TREM2 plays a significant role in regulating the early bactericidal innate immune responses during mycobacterial infection." (PMID 33863908, 2021).
myocardial ischemia (1 paper, 2024). A disorder of cardiac function caused by insufficient blood flow to the muscle tissue of the heart. "Remarkably, macrophages co-expressing Spp1 and Trem2 were identified within the infarct zone of the mouse myocardial ischemia-reperfusion model." (PMID 38449872, 2024).
neuroblastoma (1 paper, 2023). Neuroblastoma (NB) is the most common solid, extracranial childhood tumor. "shRNA-mediated YY1 silencing significantly reduced the activity of the TREM2 minimal promoter and TREM2 protein levels in the microglial cell line BV2 and the neuroblastoma Neuro2A." (PMID 37044212, 2023).
Neurodegeneration (1 paper, 2017). Progressive loss of neural cells and tissue. "AD and other neurodegeneration diseases are most probably due to reduced shedding or dysfunction of TREM2." (PMID 29180839, 2017).
Neurofibrillary tangles (1 paper, 2017). Pathological protein aggregates formed by hyperphosphorylation of a microtubule-associated protein known as tau, causing it to aggregate in an insoluble form. "Tau models of AD also show increased TREM2 levels, however, TREM2 is only increased long after neurofibrillary tangle development in these models, consistent with TREM2 upregulation at late stages of disease progression in postmortem AD brain tissue." (PMID 28768545, 2017).
ocular infection (1 paper, 2018). "We showed above that activated caspase-1 and pyroptosis were markedly enhanced in Trem2−/− corneas, and caspase-1 was involved in response to P. aeruginosa ocular infection." (PMID 29887864, 2018).
oral squamous cell carcinoma (1 paper, 2022). "However, the role of TREM2 in oral squamous cell carcinoma (OSCC) and its expression in tumor-associated macrophages (TAMs) are unknown." (PMID 36230558, 2022). "We showed that TREM2 expression in immune cells, among which were macrophages in peripheral blood mononuclear cells and tumor-associated macrophages, was associated with advanced tumor stages and reduced survival rates in oral squamous cell carcinoma (OSCC) patients." (PMID 36230558, 2022).
Osteopenia (1 paper, 2025). Osteopenia is a term to define bone density that is not normal but also not as low as osteoporosis. "Specifically, TREM2 KO mice demonstrate osteopenia (reduced bone mass), mirroring the bone lesions observed in NHD patients." (PMID 41168805, 2025).
ovarian serous cystadenocarcinoma (1 paper, 2021). A malignant serous cystic epithelial neoplasm arising from the ovary. "In contrast, TREM2 is predicted to be a negative regulator of the ribosome, RNA binding, snRNA, and other metabolic processes in CESC, STAD, KIRP, ovarian serous cystadenocarcinoma (OV), READ, and SKCM." (PMID 33679809, 2021).
pancreatic adenocarcinoma (1 paper, 2025). "The authors found that monocytes terminally differentiate into two TAM populations, defined by Trem2 or Hif1a expression, in a murine model of pancreatic adenocarcinoma." (PMID 40523200, 2025).
papillary thyroid cancer (1 paper, 2024). "Both NR4A1 and TREM2 are regulated by thyroid hormones and promote papillary thyroid cancer progression." (PMID 39719972, 2024).
Pleuritis (1 paper, 2014). Inflammation of the pleura. "Lung histology revealed that the levels of interstitial inflammation, pleuritis and edema formation were greatly decreased in mice deficient for TREM-2 compared to WT mice." (PMID 24945405, 2014).
Pneumocystis infection (1 paper, 2024). "In our study, Trem2 knockdown contributed to the reduced Pneumocystis burden and lung injury, which underlines the possibility that targeting Trem2 could be a new approach for control of Pneumocystis infection beyond neurodegenerative disease, obesity-related metabolic syndrome, and cancer." (PMID 38317180, 2024). "We also investigate the role of Trem2 in resolving the Pneumocystis infection by depletion of Trem2 in mouse models." (PMID 38317180, 2024). "Given the potential important role of PAMs in PCP, we sought to determine the surface markers of PAMs and we found that IM (CD45+ CD64+ MerTk+ SiglecF−) was the major cell population responsible for the Trem2 expression pattern after Pneumocystis infection." (PMID 38317180, 2024). "In addition, the expression of Trem2 in IMs was significantly increased after Pneumocystis infection, especially in the recovery stage." (PMID 38317180, 2024).
progressive supranuclear palsy (1 paper, 2023). A rare late-onset neurodegenerative disease characterized by supranuclear gaze palsy, postural instability, progressive rigidity, and mild dementia. "The MS4A gene cluster is a key modulator of soluble TREM2 that has been implicated in AD and progressive supranuclear palsy (PSP) pathogenesis and might provide new treatment opportunities." (PMID 38001994, 2023).
pulmonary disease (1 paper, 2021). "Gal3 binds and activates TLR4 and TREM2, a process associated with lung diseases and pulmonary fibrosis." (PMID 35069217, 2021). "Gal3 binds to and activates TREM2 and TLR4, both of which have been associated with pulmonary disease, including fibrosis." (PMID 35069217, 2021).
relapsing-remitting MS (1 paper, 2024). "Notably, a recent clinical study uncovered a significant positive correlation between IL-9 and TREM2 levels in the cerebrospinal fluid (CSF) of relapsing-remitting MS patients." (PMID 38745307, 2024).
Respiratory tract infection (1 paper, 2014). An infection of the upper or lower respiratory tract. "This work is the first to disclose a role for TREM-2 in clinically relevant respiratory tract infections and demonstrates a previously unknown link between TREM-2 and opsonin production within the lungs." (PMID 24945405, 2014). "Triggering receptor expressed on myeloid cells (TREM)-2 was proposed to negatively regulate TLR-mediated responses and enhance phagocytosis by macrophages, but the role of TREM-2 in respiratory tract infections is unknown." (PMID 24945405, 2014).
retinal disease (1 paper, 2016). "Although we examined miRNA-34a and TREM2 levels in 21 carefully selected human sporadic AMD and age-matched control retina other miRNAs or other genetic factors may play ancillary roles in phagocytosis in this retinal disease, especially in diverse human population sets." (PMID 26949937, 2016).
Rett syndrome (1 paper, 2023). A severe neurodevelopmental disorder affecting the central nervous system.
schistosomiasis (1 paper, 2023). An infectious disease caused by parasitic trematodes of the genus Schistosoma that colonize human blood vessels and release eggs that can cause granulomatous reactions leading to acute (swimmer's itch or acute schistosomiasis syndrome) or chronic disease. "To test this hypothesis, in this study, we used Trem2−/− mice infected with S. japonicum to observe the role of TREM2 in macrophage polarization in schistosomiasis." (PMID 37430471, 2023). "In summary, our study suggests that TREM2 may be involved in M2 macrophage polarization during schistosomiasis." (PMID 37430471, 2023). "In conclusion, S. japonicum‐infection may induce TREM2 expression in mouse livers and TREM2 may be involved in M2 macrophage polarization during schistosomiasis." (PMID 37430471, 2023). "Collectively, these results suggest that TREM2 may be involved in M2 macrophage polarization in schistosomiasis." (PMID 37430471, 2023). "We speculate that TREM2 participates in M2 macrophage polarization in schistosomiasis." (PMID 37430471, 2023). "However, it has not been reported whether TREM2 is related to M1 or M2 macrophage polarization in schistosomiasis." (PMID 37430471, 2023).
skin cancer (1 paper, 2023). "Within the highly proliferative neighborhood, we find that TREM2+ skin cancer-associated macrophages (SCAMs) support the proliferation of a distinct tumor epithelial population through an immunosuppression-independent manner via oncostatin-M/JAK-STAT3 signaling." (PMID 37164949, 2023). "Here we use single-cell and spatial expression approaches to identify a distinct TREM2+ VCAM1+ macrophage population within the highly proliferative neighborhood of naïve human BCCs, which we call skin cancer-associated macrophages (SCAMs)." (PMID 37164949, 2023).
staphylococcus aureus infection (1 paper, 2021). An infectious process in which the bacteria Staphylococcus aureus is present. "KEGG Pathway analysis identified enrichment of genes involved in immune-related pathways such as “complement and coagulation cascades” and “staphylococcus aureus infection” in the downregulated DEGs in female B6.Trem2*R47H mice." (PMID 34707490, 2021).
vasculitis (1 paper, 2021). "In addition, specific pathological features in the form of prominent vasculitis and edema, indicating accelerated inflammation, were observed in the lungs of Trem2−/− but not WT mice." (PMID 33863908, 2021).
ZIKV infection (1 paper, 2024). "We found that the expression of a panel of genes known to be specifically induced by microglial activation, including Clec7a, Aif1, Gfap, and Trem2, was significantly increased upon ZIKV infection." (PMID 39273400, 2024).
tumor (300 papers, 2014 to 2026). "Triggering receptor expressed on myeloid cells 2 (TREM2) has emerged as a key immunosuppressive target on tumour-associated macrophages (TAMs), where it coordinates protumorigenic and anti-inflammatory functions within the tumour microenvironment (TME)." (PMID 41562407, 2026). "Across cohorts, TREM2+ tumour-associated macrophages (TAMs) accumulate within tumours, correlate with worse outcomes, and exhibit ligand–receptor programmes that recruit Tregs and dampen cytotoxic T-cell function." (PMID 41301037, 2025). "Functionally, these TREM2+ tumor-associated macrophages (TAMs) inhibit cytotoxic T lymphocyte (CTL) recruitment and activation, facilitate extracellular matrix (ECM) remodeling, and promote an immune-excluded tumor architecture." (PMID 40821795, 2025). "PY314, another humanized monoclonal antibody, functions as a TREM2 antagonist, effectively depleting tumor-associated macrophages." (PMID 40552184, 2025). "For instance, macrophages marked by high expression of TREM2 represent a distinct subpopulation implicated in immune suppression and tumor progression across cancers." (PMID 40330466, 2025). "Lastly, heterogeneity in TREM2 gene expression and mutations raises the possibility of off-tumor risks or long-term effects on central immune regulation, necessitating careful patient screening and extended follow-up in clinical settings." (PMID 40821795, 2025). "At the immune stratum, ADM recruits MDSCs and TREM2-positive tumor-associated macrophages (TAMs) to tumor regions, suppressing CD8+ T cell cytotoxic activity." (PMID 41450464, 2025). "Next, we conducted immunohistochemistry (IHC) analysis on tumors obtained from the orthotopic HCC model to investigate the impact of TREM2 on the composition of major immune cell populations associated with tumor growth." (PMID 39838454, 2025). "The proportion of cleaved caspase-3+ cells in tumors from Trem2−/− mice was significantly greater than that in tumors from WT mice, suggesting enhanced tumor cell killing after Trem2 deficiency." (PMID 39838454, 2025). "ART, recognized as a TREM2 inhibitor, has exhibited effectiveness in selectively influencing tumor-associated monocytes by targeting TREM2, thereby eliciting an anti-tumor effect." (PMID 39744236, 2025). "In human tumors, TREM2 is mainly expressed in tumor-associated macrophages (TAMs) and is often associated with immune suppression and poor prognosis." (PMID 40242752, 2025). "To test this, we performed immunohistochemistry against CD163, a putative M2-polarisation marker and TREM2, a protein associated with immunosuppressive activity in tumour-associated microglia/macrophages." (PMID 39948623, 2025). "Further analysis using the TIMER (Tumor Immune Estimation Resource) database revealed that TREM2 is closely associated with the infiltration of various immune cells and favorable prognosis in SKCM patients." (PMID 40242752, 2025). "Within the macrophages, we identified two clusters of tumor-associated macrophages (TAMs; Fcgr2b+, Ccl4+, Trem2+) and one enriched in complement genes (C4b+, Cfp+, C1qb+)." (PMID 38570533, 2024). "Metabolite ceramide leads to reprogramming of macrophages toward immune suppressive TREM2+ tumor associated macrophages, which promote CD8 T cells exhaustion." (PMID 38302493, 2024). "Cluster 22 showed high expression levels of several microglia/macrophages genes including TREM2, which was linked before to the pro-tumorigenic properties of tumor-associated macrophages in various cancers." (PMID 38499808, 2024). "TREM2 deficiency or anti-TREM2 targeting in combination with anti-PD-1 therapy diminishes tumor growth, promotes tumor regression, and induces a proinflammatory program in macrophages in vivo." (PMID 39516356, 2024). "Phase I clinical trial has been leading in advanced refractory tumors using specific TREM2 mAb against tumor-associated macrophages expressing TREM266." (PMID 38972873, 2024).
tumor (continued). "In recent years, TREM2 has been discovered to be widely expressed on the surface of monocyte-macrophage lineage cells as well, and it is a marker for tumor-associated macrophages (TAMs) in a variety of tumor types." (PMID 38725629, 2024). "TREM2 has been implicated in fostering an immunosuppressive tumor microenvironment and is expressed in tumor-associated macrophages, correlating negatively with cancer prognosis." (PMID 39323470, 2024). "Another study confirmed these findings and found that TREM2 deficiency and anti-TREM2 mAb treatment delayed the growth of transplanted tumors and enhanced anti-PD-1 immunotherapy in mice by remodeling the tumor macrophage landscape." (PMID 38779685, 2024). "Depletion of these macrophages in TREM2 KO mice was associated with delayed tumor growth, indicating the tumor-promoting role of these macrophages in the tumor microenvironment." (PMID 38942020, 2024). "With regard to myeloid cells, the liver-resident macrophages and inflammatory monocyte/macrophages were markedly replaced by tumor-associated macrophages (TAMs), with TREM2+ and UBE2C+ TAMs enriched in PTs, while SPP1+ and WDR45B+ TAMs in MTs." (PMID 38414027, 2024). "Our results are thus in line with research looking at TREM2 function in other tissues like lung macrophages or tumor-associated macrophages." (PMID 37198381, 2023). "TREM2 has primary been shown to be expressed on the surface of cells in the tumor associated macrophage (TAM) and tumor-infiltrating myeloid cells, no TREM2 was detected in DCs or lymphoid cells in tumor microenvironment (TME)." (PMID 37563723, 2023). "By playing a part in tumor-associated macrophages (TAMs) and myeloid-derived suppressor cells (MDSCs), TREM2 participated in facilitating an immune-suppressive TME in numerous cancers, including lung cancer, gastric cancer, and glioma." (PMID 36844870, 2023). "TREM2 is mainly expressed on the surface of tumor-associated macrophages (TAMs) and functions as an essential phenotypic marker for both TAMs and monocytes with potent immunosuppressive activity." (PMID 37563723, 2023). "On the other hand, another independent study showed that use of anti-TREM2 monoclonal antibody modulated and suppressed the tumor-associated macrophage population and also led to the infiltration of CD8+ tumor associated lymphocytes in tumor microenvironment." (PMID 37335084, 2023). "These analyses revealed that the TREM2 expression levels were significantly associated with tumor-infiltrating immune cells." (PMID 36741909, 2023). "A closer examination of the tumor microenvironment (TME) reveals that TREM2 is differentially expressed across various tumor-associated macrophage (TAM) subpopulations." (PMID 38203185, 2023). "Further experiments showed that TREM2+ tumor-associated macrophages exist in various types of tumors and co-express CD68, CD163, and CSF1R." (PMID 37858183, 2023). "Characterization of tumor immune cell infiltration in BRCA-ness demonstrated an association with suppressive tumor associated TREM2 macrophages expressing marker genes, such as LILRB4 and ITGB2, which were found to be downregulated by combination therapy." (PMID 37872395, 2023). "The upregulated Trem2 level was able to inhibit the activation of NF-kB and induce macrophages M2 polarized in microglia and tumor-associated macrophages." (PMID 37212865, 2023). "In accordance, high TREM2 expression on tumour myeloid cells is associated with a poor survival rate in patients with colorectal carcinoma or triple-negative breast cancer." (PMID 36161514, 2023). "In animal studies, TREM2 expression was shown to be induced by M-CSF, IL-4, and IL-13 stimulation of mouse macrophages in vitro and to be present in tumor-associated suppressive M2-like macrophages." (PMID 37198381, 2023). "TREM2+ TAMs have also been associated with Tex in a mouse tumor model, and TREM2 deficiency or anti-TREM2 mAb treatment curbed tumor growth in mice and improved tumor sensitivity to immunotherapy." (PMID 37187751, 2023).